DNAJB14 (DnaJ heat shock protein family (Hsp40) member B14)
Description:
Acts as a co-chaperone with HSPA8/Hsc70; required to promote protein folding and trafficking, prevent aggregation of client proteins, and promote unfolded proteins to endoplasmic reticulum-associated degradation (ERAD) pathway. Acts by determining HSPA8/Hsc70's ATPase and polypeptide-binding activities. Can also act independently of HSPA8/Hsc70: together with DNAJB12, acts as a chaperone that promotes maturation of potassium channels KCND2 and KCNH2 by stabilizing nascent channel subunits and assembling them into tetramers. While stabilization of nascent channel proteins is dependent on HSPA8/Hsc70, the process of oligomerization of channel subunits is independent of HSPA8/Hsc70. When overexpressed, forms membranous structures together with DNAJB12 and HSPA8/Hsc70 within the nucleus; the role of these structures, named DJANGOs, is still unclear. (Microbial infection) In case of infection by polyomavirus, involved in the virus endoplasmic reticulum membrane penetration and infection.
Synonyms: FLJ14281; EGNR9427; PRO34683
Tractability: Antibody: UniProt predicts a signal peptide or a membrane-spanning region. PROTAC: ubiquitination databases record sites on it; its protein half-life has been measured.
Gene: Protein-coding gene on chromosome 4 (99,896,248 to 99,946,653, reverse strand). Ensembl gene ENSG00000164031.
Subcellular location: Endoplasmic reticulum membrane; Nucleus membrane
Subcellular location (Human Protein Atlas): Endoplasmic reticulum
Gene Ontology:
Molecular function: Hsp70 protein binding; protein binding
Biological process: protein folding; protein-containing complex assembly; cellular response to misfolded protein
Cellular component: endoplasmic reticulum; endoplasmic reticulum membrane; membrane; nuclear membrane
Genetic constraint (gnomAD): Loss-of-function variants: 19 observed, 43.58 expected, observed/expected ratio (o/e) 0.44, 90% interval 0.3 to 0.64. The upper end of that interval is the gene's LOEUF score, 0.64, which puts it in group 2 of 6, group 1 being the genes least tolerant of losing a copy. Missense variants: 312 observed, 463.5 expected, observed/expected ratio (o/e) 0.67, 90% interval 0.61 to 0.74. Synonymous variants: 138 observed, 160.91 expected, observed/expected ratio (o/e) 0.86, 90% interval 0.75 to 0.99.
Homologues: Orthologues: chimpanzee DNAJB14 (100% identical), macaque DNAJB14 (99% identical), dog DNAJB14 (98% identical), pig DNAJB14 (98% identical), rabbit DNAJB14 (97% identical), mouse Dnajb14 (93% identical), rat Dnajb14 (93% identical), guinea pig DNAJB14 (91% identical), tropical clawed frog dnajb14 (71% identical), zebrafish dnajb14 (63% identical), Drosophila melanogaster CG3061 (40% identical), Caenorhabditis elegans dnj-1 (38% identical), and 5 more. Paralogues in human: DNAJB12 (52% identical), DNAJB4 (20% identical), DNAJB11 (19% identical), DNAJB6 (19% identical), DNAJB1 (19% identical), DNAJB5 (18% identical), DNAJB8 (18% identical), DNAJB2 (16% identical), DNAJB13 (16% identical), DNAJB7 (16% identical), DNAJB9 (14% identical).
Diseases named in the same sentence as DNAJB14 in open-access papers:
DNAJB14 is named in the same sentence as 3 diseases in open-access papers, as found by Europe PMC text mining. Sharing a sentence is not in itself a finding about the gene and the disease. The quoted sentences say what the papers report.
infection (2 papers, 2014). The state of being infected such as from the introduction of a foreign agent such as serum, vaccine, antigenic substance or organism. "In the course of investigating the requirement for the cellular DNAJB12 and DNAJB14 proteins (B12 and B14, respectively) for infection by SV40, we examined HeLa cells that expressed HA-tagged B12." (PMID 24732912, 2014). "We recently reported that two closely related ER proteins, DNAJB12 (designated B12) and DNAJB14 (B14), are essential for infection by the DNA tumor virus, simian virus 40 (SV40)." (PMID 24732912, 2014). "For instance, Dnaja2, Dnajb2, Dnajb12a, Dnajb12b, Dnajb14, Dnajc5ab, Dnajc5gb, Dnajc7, Dnajc16, and Dnajc26 were up-regulated only at 3 days after infection, but not at 14 days after infection; similarly, Dnajc28 was up-regulated only at 14 days after infection, but not at 3 days after infection." (PMID 25542027, 2014).
cancer (1 paper, 2025). A tumor composed of atypical neoplastic, often pleomorphic cells that invade other tissues. "Together, these findings establish that DNAJB12, DNAJB14, and SGTA are required for PDIA4 reflux to the cytosol, where it binds caspase-3 and promotes cancer cell resistance." (PMID 41120732, 2025).
tumor (1 paper, 2020). "The expression levels of DNAJB1, DNAJB5, DNAJB6, DNAJB11, DNAJB12, DNAJB13, and DNAJB14 were significantly upregulated in the tumor tissues." (PMID 32984053, 2020).